MERTK (MER proto-oncogene, tyrosine kinase)
Diseases named in the same sentence as MERTK in open-access papers (continued):
Sharing a sentence is not in itself a finding about the gene and the disease.
Flavivirus Infections (1 paper, 2023). Infections with viruses of the genus FLAVIVIRUS, family FLAVIVIRIDAE. "TAM family and TIM family genes, mainly including AXL, TYRO3, MERTK and TIM-1, were suggested as putative host factors in flavivirus infection of human host cells." (PMID 37684223, 2023).
gastric adenocarcinoma (1 paper, 2024). "Here, we showed the relevance of MerTK expression as an independent factor associated with overall survival in human gastric adenocarcinoma in addition to histopathological M status using multivariant Cox regression analysis." (PMID 38545840, 2024). "Our findings demonstrate the potential value of MerTK as a prognostic biomarker for gastric adenocarcinoma." (PMID 38545840, 2024). "MerTK expression and its influence on patient survival were evaluated by immunohistochemistry in a cohort of 140 patients with gastric adenocarcinoma." (PMID 38545840, 2024). "To examine the expression level of MerTK in human gastric adenocarcinoma, we selected 140 patients diagnosed with pathologically confirmed gastric adenocarcinoma." (PMID 38545840, 2024). "Therefore, the aim of this study was to analyze the relevance of MerTK in gastric adenocarcinoma and evaluate the possible therapeutic benefits of the MerTK inhibitor UNC2025 in vitro and in vivo." (PMID 38545840, 2024). "Although the tyrosine kinase MerTK has shown therapeutic relevance in several tumor entities, its potential effects in gastric adenocarcinoma have not yet been sufficiently characterized." (PMID 38545840, 2024).
Gaucher disease type I (1 paper, 2024). Gaucher disease type 1 is the chronic non-neurological form of Gaucher disease (GD) characterized by organomegaly, bone involvement and cytopenia. "Interestingly, MerTK expression is lower in Gaucher's disease type I (67.3 %, p < 0.0001) and III (65.9 %, p < 0.0001), but not changed in Gaucher's disease type II." (PMID 38341954, 2024).
gout (1 paper, 2023). A condition characterized by painful swelling of the joints, which is caused by deposition of urate crystals. "In this study, we proposed the molecular mechanism of ozone in the treatment of gout pain through AMPK/Gas6/MerTK/SOCS3/MMP9 for the first time." (PMID 38066599, 2023). "Ozone reduces inflammation and alleviates gout pain by activating AMPK to up-regulate Gas6/MerTK/SOCS3 signaling pathway." (PMID 38066599, 2023).
Headache (1 paper, 2024). Cephalgia, or pain sensed in various parts of the head, not confined to the area of distribution of any nerve. "This study points to a possible role for MERTK in headache pathophysiology by showing strong expression in the glial cells of the TG, and an upregulation of MERTK and its ligand Gal-3 in CH patients." (PMID 38783191, 2024).
helminth infection (1 paper, 2021). "In the context of IL-4-inducing helminth infection, genetic ablation of phagocytic receptors, MerTK and AXL, leads to reduced proliferation of macrophages and induction of anti-inflammatory and tissue repair genes." (PMID 33668084, 2021).
Hepatitis (1 paper, 2022). Inflammation of the liver. "However, animals develop hepatitis with hepatic accumulation of macrophages with M2 phenotype expressing CD163, MerTK, and TGF-β." (PMID 35639478, 2022).
HIV-1 infection (1 paper, 2020). The type species of lentivirus and the etiologic agent of acquired immunodeficiency syndrome (AIDS). "As we described and observed before and herein, cmMTB-treated cells were positive for the M(IL-10) markers (CD16+CD163+MerTK+ and phosphorylated STAT3), and displayed a high rate of HIV-1 infection, as compared to those treated with cmCTR." (PMID 32223897, 2020).
Huntington disease (1 paper, 2024). Huntington disease (HD) is a rare neurodegenerative disorder of the central nervous system characterized by unwanted choreatic movements, behavioral and psychiatric disturbances and dementia. "In artificial tissues, we found that MerTK expression is 21.4 % (p = 0.0124) and 35.2 % (p < 0.0001) lower in Huntington's disease and psoriasis vulgaris, respectively." (PMID 38341954, 2024).
Hyperglycemia (1 paper, 2024). An increased concentration of glucose in the blood. "Mechanistically, hyperglycemia decreased the expression of MerTK on macrophages." (PMID 38614985, 2024).
intracerebral hemorrhage (1 paper, 2024). A cerebrovascular disorder characterized by bleeding into one or both cerebral hemispheres including the basal ganglia and the cerebral cortex. "In a murine model, the transcriptional levels of Axl, MerTK, and their ligand Gas6 increase within 24 hours post-intracerebral hemorrhage (ICH), and deficiency of Axl/MerTK impairs macrophage-mediated erythrophagocytosis in ICH." (PMID 39660125, 2024).
invasive ductal carcinomas (1 paper, 2020). "In one out of eight invasive ductal carcinomas, both immune infiltrate and cancer cells positive for MerTK were observed (middle and left)." (PMID 33101282, 2020).
kidney damage (1 paper, 2021). "In particular, we asked whether improved kidney damage following Gas6 administration was associated to the activation of Axl, MerTK or both." (PMID 33803290, 2021).
larynx carcinomas (1 paper, 2016). A primary or metastatic malignant neoplasm involving the larynx. "However, we observed lower MERTK protein levels in tumors from the oral cavity compared to pharynx and larynx carcinomas in the Bonn HNSCC cohort (p = 0.008)." (PMID 27081701, 2016).
Lewis Lung Carcinoma (1 paper, 2019). "To assess the therapeutic potential for combination treatment targeting NF-κB and Gas6-MerTK, we injected Lewis Lung Carcinoma cells subcutaneously and treated mice with Bay 11-70852 (NF-κB inhibitor) and/or Foretinib (MerTK inhibitor)." (PMID 31903163, 2019).
Lewy body dementia (1 paper, 2024). A progressive form of dementia characterized by the presence of protein deposits called Lewy bodies in the midbrain and cerebral cortex, and loss of cholinergic and dopaminergic neurons. "Some clusters predominantly composed of microglia from Parkinson’s disease/Lewy body dementia patients had particularly high expression of MERTK (Clusters 7, 8, 10, 15 and 16)." (PMID 37671615, 2024). "Upregulation of MerTK protein expression in synucleinopathies was next verified by western blotting using substantia nigra tissues from nine Lewy body dementia patients and nine control donors." (PMID 37671615, 2024). "At the whole tissue level, accumulation of α-syn S129p in the brains of Lewy body dementia patients was unaccompanied by MerTK protein upregulation." (PMID 37671615, 2024). "Moreover, MERTK mRNA expression was found to be only modestly increased in microglia from Parkinson’s disease/Lewy body dementia patients compared to control donors." (PMID 37671615, 2024). "Altogether, the data suggest a lack of substantial upregulation in MerTK expression in synucleinopathies such as Lewy body dementia." (PMID 37671615, 2024). "Our data exclude the possibility that a dysregulated MerTK pathway is responsible for α-syn fibril accumulation in Parkinson’s disease/Lewy body dementia, since no downregulation of MerTK expression was observed." (PMID 37671615, 2024). "In contrast, expression of homeostatic markers such as CX3CR1 and TGFBR1, as well as MERTK were unaffected by in vitro α-syn PFF exposure, suggesting α-syn fibrils are direct drivers of some, but not all, microglial transcriptomic changes in late-stage Parkinson’s disease/Lewy body dementia." (PMID 37671615, 2024).
long QT syndrome (1 paper, 2017). "UNC1062 is a potent and selective MerTK inhibitor with minimal effects on potassium channel, which could cause long QT syndrome." (PMID 29228560, 2017).
lupus-like syndromes (1 paper, 2015). "In fact, lupus-like syndromes arise because of defective clearance of ACs owing to impaired expression or function of efferocytic molecules, as occurs in mice lacking functional MerTK." (PMID 25972766, 2015).
macular degeneration (1 paper, 2020). Loss of vision in the central portion of the retina (macula), secondary to retinal degeneration. "Pathogenic variants of MERTK are known to cause severe, faster, and early onset RP with worse macular degeneration." (PMID 32976546, 2020).
mantle cell lymphoma (1 paper, 2020). Mantle cell lymphoma is a rare form of malignant non-Hodgkin lymphoma affecting B lymphocytes in the lymph nodes in a region called the ``mantle zone''. "–48 MERTK is not expressed on the normal lymphocytes but has been found to be expressed in a majority of lymphoblasts from patients with T-cell leukemia, certain subsets of B-cell leukemia, and mantle cell lymphoma." (PMID 32492107, 2020).
meningioma (1 paper, 2023). A generally slow growing tumor attached to the dura mater. "It is likely that this difference in UNC2025 sensitivity of meningioma patient-derived spheroids and monolayers is caused by the decreased gene expression of the target MERTK in monolayers, making the cells less dependent on MERTK signalling." (PMID 38102708, 2023). "Moreover, in addition to meningioma cells, MERTK is expressed by tumour-associated macrophages." (PMID 38102708, 2023). "Indeed, unpublished work by our group has demonstrated the upregulation of MERTK expression in meningiomas." (PMID 38102708, 2023). "We then used our spheroid model and provided evidence for the potential of the MERTK inhibitor UNC2025 and the HDAC inhibitor TSA as a novel therapeutic strategy for the treatment of meningiomas." (PMID 38102708, 2023). "We found that combination therapy using the MER tyrosine kinase (MERTK) inhibitor UNC2025 and the histone deacetylase (HDAC) inhibitor Trichostatin A (TSA) effectively decreased meningioma spheroid viability and proliferation." (PMID 38102708, 2023). "Using this model, we demonstrated the therapeutic potential of the combination therapy of the MERTK inhibitor UNC2025 and the HDAC inhibitor Trichostatin A (TSA) to treat patient derived WHO grade 1 and grade 2 meningiomas." (PMID 38102708, 2023).
migraine (1 paper, 2024). "Although MERTK has not been genetically associated to migraine in GWAS, increased Gal-3 in migraine patients have been observed in several studies, and we hypothesize that the Gal-3 - MERTK pathway has relevance for both migraine and CH." (PMID 38783191, 2024).
myocarditis (1 paper, 2025). Myocarditis is a condition that is characterized by inflammation of the heart muscle (myocardium). "During the acute phase of myocarditis, a significant quantity of IL-17a is present, which facilitates the shedding of MERTK and influences the expression profile of genes associated with inflammation and tissue remodeling." (PMID 41590849, 2025).
neuropathic pain (1 paper, 2024). Chronic pain caused by damage to nerve fibers. "Similarly, the AMPK inhibitor CC and the MerTK inhibitor UNC2541 were used to verify the role of AMPK and MerTK activation in ozone therapy for neuropathic pain." (PMID 39628480, 2024).
night blindness (1 paper, 2011). Inability to see clearly in dim light. "The patients with MERTK mutations had a severe phenotype with onset of night blindness in the first decade, a rapidly progressive deterioration of central vision, and severely affected visual fields during the second decade." (PMID 21677792, 2011).
occlusion artery disease (1 paper, 2024). "As expected, the machine learning disease pathways show that MerTK gene deficiency is associated with occlusion artery disease, heart dysfunction and brain disorders." (PMID 38646649, 2024).
Osteopenia (1 paper, 2022). Osteopenia is a term to define bone density that is not normal but also not as low as osteoporosis. "Therefore, MERTK represents a novel target whose inhibition counteracts cancer-induced osteopenia through stimulation of osteoblast function, whereas TYRO3 represents a bone protective factor." (PMID 36509738, 2022).
Parkinson disease (1 paper, 2024). A progressive degenerative disorder of the central nervous system characterized by loss of dopamine producing neurons in the substantia nigra and the presence of Lewy bodies in the substantia nigra and locus coeruleus. "Overall, these results suggest that some rare, functionally deleterious MERTK variants may be associated with Parkinson’s disease, however these findings require additional replications." (PMID 37671615, 2024). "Lack of MerTK upregulation accompanying α-syn accumulation in the human brain and genetic associations between rare MERTK variants and Parkinson’s disease suggest MerTK as a potential therapeutic target to enhance α-syn fibril clearance by microglia in synucleinopathies." (PMID 37671615, 2024). "However, specific genetic variants that are deleterious to MerTK function could be associated with Parkinson’s disease according to the result of our burden analysis." (PMID 37671615, 2024). "A significant association between MERTK variants with CADD score ≥20 (representing the top 1% of potentially deleterious variants) and Parkinson’s disease was found in the UKBB cohort (P = 0.002)." (PMID 37671615, 2024). "Consistent with the in vitro observations, only MERTK but not AXL variants were genetically associated with Parkinson’s disease cases in the UKBB cohort." (PMID 37671615, 2024). "Taken together, our findings define a novel role for MerTK in mediating the uptake of alpha-synuclein fibrils by human microglia, with possible involvement in limiting alpha-synuclein spread in synucleinopathies such as Parkinson’s disease." (PMID 37671615, 2024).
peripheral arterial disease (1 paper, 2024). A disorder of the arteries supplying the upper and lower extremity and the visceral organs. "Finally, we summarized the associated disease pathways based on -log (p value), showing that MerTK-/- may contribute to infection, brain dysfunction, heart dysfunction, peripheral arterial disease, sclerotic lesion, and artery occlusion." (PMID 38646649, 2024).
pharynx carcinoma (1 paper, 2016). A primary or metastatic malignant neoplasm that affects the pharynx. "This fits nicely with the cell models used for our in-vitro experiments, since HN cells with almost no MERTK expression are derived from oral-squamous cancer whereas Detroit 562 cells with high MERTK expression were isolated from a pleural effusion from a patient with pharyngeal carcinoma." (PMID 27081701, 2016). "To investigate whether MERTK could serve as a therapeutic target in HNSCC we treated Detroit 562 cells, derived from a pleural effusion of a patient with pharynx carcinoma, that strongly express MERTK and HN cells with little MERTK expression with UNC1062, a selective MERTK inhibitor." (PMID 27081701, 2016).
Pneumocystis infection (1 paper, 2024). "Given the potential important role of PAMs in PCP, we sought to determine the surface markers of PAMs and we found that IM (CD45+ CD64+ MerTk+ SiglecF−) was the major cell population responsible for the Trem2 expression pattern after Pneumocystis infection." (PMID 38317180, 2024).
polycythemia (1 paper, 2023). Abnormally high mass or concentration of red blood cells in the blood, either due to an increase in erythropoiesis or a decrease in plasma volume. "Here, we show that blocking the CD47-SIRPα interaction results in the correction of polycythemia in a PV mouse model, which correlates with the expansion of splenic MerTK+ Mdcs and increased phagocytic activity of JAK2 mutant splenic macrophages against RBCs." (PMID 37095207, 2023).
proteinopathies (1 paper, 2024). "MerTK has been receiving increasing attention as a potential therapeutic target in proteinopathies over recent years." (PMID 37671615, 2024).
schistosomiasis (1 paper, 2014). An infectious disease caused by parasitic trematodes of the genus Schistosoma that colonize human blood vessels and release eggs that can cause granulomatous reactions leading to acute (swimmer's itch or acute schistosomiasis syndrome) or chronic disease. "We asked whether macrophages were proliferating in the liver during schistosomiasis by injecting mice with BrdU and then using flow cytometry to detect BrdU in MerTK+CD64+ macrophages at times thereafter." (PMID 25144366, 2014).
sickle cell disease (1 paper, 2026). Sickle cell anemias are chronic hemolytic diseases that may induce three types of acute accidents: severe anemia, severe bacterial infections, and ischemic vasoocclusive accidents (VOA) caused by sickle-shaped red blood cells obstructing small blood vessels and capillaries. "Here, we investigate the contribution of PROS1 and MerTK to the phagocytosis of intact RBC and eryghosts in healthy subjects and patients with sickle cell disease (SCD)." (PMID 41137641, 2026).
silicosis (1 paper, 2024). Silicosis is a respiratory disease caused by breathing in (inhaling) silica dust. "We employed MerTk and Axl defective mice to induce acute silicosis by a single exposure to crystalline silica particles (20 mg/50 μL)." (PMID 38774866, 2024). "In agreement, we found that mice lacking Axl are more susceptible to silicosis than MerTk-/- or WT mice." (PMID 38774866, 2024). "This study provides evidence that MerTk and Axl are specialized to orchestrate apoptotic cell clearance in different settings, where they play constitutive and significant roles in lung immunological homeostasis and silicosis disease resolution, respectively." (PMID 38774866, 2024). "This study provides strong evidence that MerTk and Axl are specialized to orchestrate apoptotic cell clearance in different settings, where they play constitutive and significant roles in lung immunological homeostasis and silicosis resolution, respectively." (PMID 38774866, 2024). "While MerTk regulates inflammation in healthy tissues that are constantly exposed to microbiota, antigens, and cellular renewal, and in which billions of apoptotic cells are generated and cleared on a regular basis, Axl regulates inflammation and helps to restore homeostasis during silicosis." (PMID 38774866, 2024).
Splenomegaly (1 paper, 2025). Abnormal increased size of the spleen. "In addition, HCQ treatment significantly attenuated splenomegaly observed in PIL mice, accompanied by increased expression of MerTK and Gas6 in the spleen, suggesting that HCQ may promote restoration of efficient efferocytosis systemically." (PMID 40589760, 2025).
synucleinopathies (1 paper, 2024). "The current study explored the function of MerTK in the microglial uptake of alpha-synuclein fibrils which play a causative role in the pathobiology of synucleinopathies." (PMID 37671615, 2024).
T-cell acute lymphoblastic leukemia (1 paper, 2024). Acute lymphoblastic leukemia of T-cell origin. "Studies in pediatric T-cell acute lymphoblastic leukemia showed increased MerTK expression, while inhibition of MerTK curtailed T-cell precursor expansion and induced apoptosis." (PMID 39845889, 2024).
viral hepatitis C (1 paper, 2021). "The rs4374383 non-coding variant in the macrophage c-mer tyrosine kinase (MERTK), a tyrosine kinase that initiates the removal of dying cells by phagocytes and that mediates HSCs activation, protects against fibrosis in both NAFLD and in viral hepatitis C, eliciting MERTK down-modulation." (PMID 34680476, 2021).